TRBV7-6 (T cell receptor beta variable 7-6)
Description:
V region of the variable domain of T cell receptor (TR) beta chain that participates in the antigen recognition. Alpha-beta T cell receptors are antigen specific receptors which are essential to the immune response and are present on the cell surface of T lymphocytes. Recognize peptide-major histocompatibility (MH) (pMH) complexes that are displayed by antigen presenting cells (APC), a prerequisite for efficient T cell adaptive immunity against pathogens. Binding of alpha-beta TR to pMH complex initiates TR-CD3 clustering on the cell surface and intracellular activation of LCK that phosphorylates the ITAM motifs of CD3G, CD3D, CD3E and CD247 enabling the recruitment of ZAP70. In turn ZAP70 phosphorylates LAT, which recruits numerous signaling molecules to form the LAT signalosome. The LAT signalosome propagates signal branching to three major signaling pathways, the calcium, the mitogen-activated protein kinase (MAPK) kinase and the nuclear factor NF-kappa-B (NF-kB) pathways, leading to the mobilization of transcription factors that are critical for gene expression and essential for T cell growth and differentiation. The T cell repertoire is generated in the thymus, by V-(D)-J rearrangement. This repertoire is then shaped by intrathymic selection events to generate a peripheral T cell pool of self-MH restricted, non-autoaggressive T cells. Post-thymic interaction of alpha-beta TR with the pMH complexes shapes TR structural and functional avidity.
Synonyms: TRBV76; TCRBV6S3A1N1T; TCRBV7S6
Gene: T-cell receptor variable (V) gene on chromosome 7 (142,492,132 to 142,492,673, forward strand). Ensembl gene ENSG00000211727.
Subcellular location: Cell membrane
Gene Ontology:
Biological process: cell surface receptor signaling pathway
Cellular component: plasma membrane
Homologues: Paralogues in human: TRBV7-7 (94% identical), TRBV7-4 (81% identical), TRBV7-9 (74% identical), TRBV7-2 (72% identical), TRBV7-3 (71% identical), TRBV7-1 (69% identical), TRBV11-1 (62% identical), TRBV11-2 (58% identical), TRBV11-3 (58% identical), TRBV12-4 (58% identical), TRBV12-3 (57% identical), TRBV12-5 (55% identical), and 39 more.